OR11H1 (olfactory receptor family 11 subfamily H member 1)
Description:
Odorant receptor.
Synonyms: OR22-1
Gene: Protein-coding gene on chromosome 22 (15,528,192 to 15,529,139, forward strand). Ensembl gene ENSG00000130538.
Subcellular location: Cell membrane
Pathways (Reactome):
Sensory Perception: Expression and translocation of olfactory receptors
Genetic constraint (gnomAD): Loss-of-function variants: 2 observed, 6.29 expected, observed/expected ratio (o/e) 0.32, 90% interval 0.13 to 1. That is too few expected variants to judge how well the gene tolerates losing a copy. Missense variants: 53 observed, 149.76 expected, observed/expected ratio (o/e) 0.35, 90% interval 0.28 to 0.44. Synonymous variants: 13 observed, 51.35 expected, observed/expected ratio (o/e) 0.25, 90% interval 0.16 to 0.4.
Homologues: Orthologues: dog OR11H12 (81% identical). Paralogues in human: OR11H12 (99% identical), OR11H2 (98% identical), OR11H6 (63% identical), OR11H4 (61% identical), OR11G2 (59% identical), OR11H7 (56% identical), OR11A1 (43% identical), OR9G1 (41% identical), OR10X1 (37% identical), OR9A1P (34% identical), OR9A2 (34% identical), OR9A4 (34% identical), and 21 more.
Diseases named in the same sentence as OR11H1 in open-access papers:
OR11H1 is named in the same sentence as 3 diseases in open-access papers, as found by Europe PMC text mining. Sharing a sentence is not in itself a finding about the gene and the disease. The quoted sentences say what the papers report.
uveitis (1 paper, 2024). An inflammatory process affecting a part of or the entire uvea. "Next, we investigated the expression of OR11H1 mRNA in intraocular tissues and cells that are involved in the uveitis pathogenesis." (PMID 38168905, 2024). "Our results suggested that OR11H1 might be a disease‐causing gene for VKH disease, providing a novel target and new strategy for the treatment of uveitis in the future." (PMID 38168905, 2024).
OR11H1 also shares sentences with these, for which no sentence is quoted: metastatic disease (1 paper); tumor (1).